CXCL11 (C-X-C motif chemokine ligand 11)
Diseases named in the same sentence as CXCL11 in open-access papers (continued):
Sharing a sentence is not in itself a finding about the gene and the disease.
cancer (181 papers, 2009 to 2026). A tumor composed of atypical neoplastic, often pleomorphic cells that invade other tissues. "Cxcl10 and Cxcl11 are chemokines implicated not only in immune disorders but also in cancer progression and T cell-mediated immune responses." (PMID 41019339, 2025). "CXCL11 is primarily associated with M1 macrophages, promoting inflammatory responses and playing significant roles in the progression of cancer and fibrotic diseases." (PMID 39548525, 2024). "CXCL11 is usually associated with cancer promotion, including proliferation, migration, angiogenesis, and T-cell infiltration." (PMID 37893029, 2023). "This suggests that the upregulation of CXCL9, CXCL10 and CXCL11 is a common event in the cancers with viral or bacterial association." (PMID 35433690, 2022). "CXCL11 is involved in the progression of various cancers, and its expression is associated with tissue infiltration by T cells." (PMID 36248969, 2022). "Cancer-associated fibroblasts secrete significantly higher levels of CXCL11 than normal fibroblasts (NFs), and CXCL11 expression is significantly elevated, indicating that CXCL11 can promote HCC cell migration." (PMID 36504808, 2022). "Similar to immunosuppressive genes, CXCL11 expression was positively associated with most immunostimulatory genes in all cancers we analyzed except THYM." (PMID 35935945, 2022). "CCL5, CXCL9, CXCL13, CXCL10, and CXCL11 were also among the top chemokine genes associated with the gene expression-based immune scores across multiple cancer types." (PMID 34030676, 2021). "Next, correlation analyses were performed in order to analyze whether the differential effects of radio(chemo) therapeutic treatment on monocytic PD-L1 and plasma CXCL11 levels of cancer patients might be associated." (PMID 38609887, 2024). "In addition to CCL5 expression, high CXCL11 expression levels were noted to be associated with a poorer prognosis in most cancers." (PMID 37627528, 2023). "In addition, increased CXCL11 expression in cancer-associated fibroblasts (CAFs) promotes the proliferation and migration of EOC cells via CXCR3." (PMID 35269786, 2022). "However, the expression level of CXCR3 in clinical cancer samples is associated with metastatic potential and patients prognosis, and the affinity of CXCL11 for CXCR3 is the highest of the three selective ligands." (PMID 33777950, 2021). "CAF-derived CXCL11 increased migration and metastasis of HCC, while cancer cell-secreted CXCL11 enhanced CD8+ T cell infiltration in a preclinical study." (PMID 39780187, 2025). "On the other hand, CXCL10 and CXCL11 have been described to enhance cancer development, possibly by promoting angiogenesis and metastasis." (PMID 40895532, 2025). "Similar observations have been reported for other genes such as CXCL11, Plk1, and CD177, where high expression levels are unexpectedly associated with better clinical outcomes in specific cancer types." (PMID 38890197, 2024). "Among chemokines, especially CCL4, CCL5, CCL8, CXCL9, CXCL10 and CXCL11 were markedly positive correlated with LAMP3 expression in most cancers." (PMID 38146591, 2024). "Based on these findings, we examined CXCR3/CXCL11-axis-mediated chemotactic activity in cancer and CD8+ T cells." (PMID 39543650, 2024). "As a key chemokine that regulates macrophage polarization, CXCL11 influences inflammatory reactions and tissue regeneration, making it an important target in the treatment of inflammatory diseases and cancer." (PMID 39548525, 2024). "Consistent with the findings of a previous study, we observed that the binding of CXCL11 to CXCR3 on CD8+ T cells enhanced the apoptotic rate of cancer cells." (PMID 39543650, 2024). "Low expression of RAMP2-AS1, a cancer suppressor, impairs the inhibition of downstream CXCL11, leading to cancer progression." (PMID 37901333, 2023).
cancer (continued). "CELSR3 is expressed in Epithelial Cells, CT83 is highly expressed in Cancer cells, Epithelial cells, and Neutrophils, and CXCL11 is expressed in Fibroblast and M1 Macrophages." (PMID 37985782, 2023). "QUE’s anti-inflammatory properties were also confirmed by the potent downregulation of pro-inflammatory chemokines, in particular the CXCR3 ligands CXCL9, CXCL10, and CXCL11, which are important players in chronic liver diseases, inflammation, and cancer." (PMID 37755981, 2023). "Reports have asserted that the CXCL9, CXCL10, and CXCL11 axes are important for immune activation in cancer therapy." (PMID 37048082, 2023). "Among them, CXCL9, CXCL10, and CXCL11 have been reported to promote cancer cell proliferation by combining with CXCR3A." (PMID 35992864, 2022). "Pro-tumor chemokines, such as CXCL8, CXCL9, CXCL10, and CXCL11, can promote cancer cell proliferation and metastasis, and our results revealed that NEIL3 expression was positively correlated with them." (PMID 36612106, 2022). "CXCL10 and CXCL11 were predominantly synthesized and produced by monocytes, endothelial cells, fibroblasts, and cancer cells under the induction of IFN-γ and TNFα." (PMID 36003333, 2022). "The results showed that there was a high correlation between CXCL11 expression and immunoregulation genes, chemokine receptors and other chemokines in almost all types of cancers." (PMID 35935945, 2022). "The different expression levels were associated with different clinical outcomes, which warrants further investigation of the specific role of CXCL11 in each cancer." (PMID 35935945, 2022). "To explore the expression of CXCL11, we analyzed the mRNA expression across cancers by integrating the GTEx and TCGA databases." (PMID 35935945, 2022). "Based on this complexity, the prognostic role of CXCL11 has been explored in a pan-cancer study with 33 types of malignancies." (PMID 36429101, 2022). "The results revealed that CXCL11 was positively related to almost all chemokine receptors in almost all cancers except LAML." (PMID 35935945, 2022). "This study first analyzed CXCL11 expression across all 33 cancers using emerging data from the TCGA and GTEx databases." (PMID 35935945, 2022). "In this study, we investigated the expression and function of CXCL11 across 33 types of cancers based on datasets from The Cancer Genome Atlas (TCGA) database and the Genotype-Tissue Expression (GTEx) database." (PMID 35935945, 2022). "The expression of CXCL11 was positively related to the StromalScore, ImmuneScore, and EstimateScore in the vast majority of cancers with statistical significance." (PMID 35935945, 2022). "Our data also showed that CXCL11 expression was positively related to all MHC genes in most cancers except DLBC." (PMID 35935945, 2022). "Our results revealed that CXCL11 expression was positively associated with CD8+ T cells and T follicular helper cells but negatively related to MDSCs in almost all cancers." (PMID 35935945, 2022). "And when additional CXCL11 was introduced into conditioned media, cancer cell migration was further enhanced." (PMID 33707417, 2021). "The expression levels of six chemokine genes (CCL5, CXCL9, CXCL13, CXCL10, CXCL11, and CCL19) were significantly associated with the image-based immune scores across all 13 tested cancer types." (PMID 34030676, 2021). "We also further analyzed the correlation between the immune cell infiltration signal and the expression of CXCL11 in the TCGA pan‐cancer cohorts and found similar results." (PMID 34047476, 2021). "Based on the multivariate Cox proportional hazards model, levels of CXCL9 and CXCL11 remained independent prognosticators for overall survival after controlling for significant covariates such as patient age and cancer stage from the univariate Cox model." (PMID 34501934, 2021).
cancer (continued). "CXCL11 not only regulates the targeted movement of cancer cells but is also involved in cancer cell entry into and out of blood vessels, immune evasion, proliferation, and angiogenesis." (PMID 32341359, 2020). "CXCL11 transcripts were significantly more abundant in cancer‐replaced nodes, while CXCL12 transcripts were significantly more abundant in cancer‐free nodes." (PMID 31755096, 2020). "In our study, we characterized a MA signature consisting of three distinct genes (Cxcl11, Gbp1, Ido1), which correlates with the presence of M1 macrophages and mature DC in various cancer cohorts available in TCGA." (PMID 32486450, 2020). "On the other hand, RNA-seq and Q-PCR analysis showed that TILRR potentiates CXCL10 and CXCL11 chemokine expression in the BT474 cancer cell line." (PMID 33031059, 2020). "Staining of tissue sections confirmed CXCL11 expression in cancer cells which were identified by glandular morphology and anti-EpCam staining (not shown)." (PMID 29163806, 2017). "Of note, CXCL10 and CXCL11 expression was significantly reduced in matched samples from colorectal liver metastasis as compared to primary cancer (n=11)." (PMID 29163806, 2017). "The high levels of CXCL11 secreted from infected MC38 cancer cells were determined in vitro and in MC38 tumors in vivo as determined by ELISA assays." (PMID 26956047, 2016). "Importantly, the C-X-C motif chemokine ligands CXCL9, CXCL10, and CXCL11 were significantly up-regulated in patients with high MOTIscores in both cancer types, suggesting the presence and activation of immune cells in these tumors." (PMID 41463470, 2025). "Enhanced levels of many cytokines related to cancer invasion and migration are found in the CMs of ET-1-treated cells, including IL-6, IL-8, CXCL11, and CXCL12, further supporting the hypothesis that ET-1 is a driver of activated fibroblasts." (PMID 38777849, 2024). "In addition, binding of CXCL11 with CXCR3 on CD8+ T cells enhanced the killing activity to cancer cells." (PMID 39543650, 2024). "Cancer‐cell‐secreted CXCL11 could promote CD8 T cell infiltration through the docetaxel‐induced release of HMGB1 in NSCLC." (PMID 36822595, 2023). "An analysis of differentially expressed genes revealed that EphA2 may exert its cancer-promoting effect through C-X-C motif chemokine ligand 11 (CXCL11)." (PMID 36478746, 2022). "Improving immunogenicity by altering the TME could be the future for cancer therapy, though the role of CXCL11 and its impact on the TME are not fully understood." (PMID 35935945, 2022). "Indeed, a recent study demonstrates that adding culture media from senescent HUVECs to cancer cells increased the cell proliferation, migration, and invasion, mainly through CXCL11." (PMID 35805077, 2022). "Therefore, we analyzed data from TCGA and the GTEx databases to investigate CXCL11 expression levels and their relationship with prognosis across cancers." (PMID 35935945, 2022). "CXCL11 was positively related to approximately all immune-related genes in almost all cancers." (PMID 35935945, 2022). "In this study, CXCL11 expression was associated with MMR genes, TMB, and MSI in certain cancers." (PMID 35935945, 2022). "CXCL11 is a major chemoattractant for effector T cells, thus CXCL11-dependent therapy may be a potential approach for cancer treatment." (PMID 36578780, 2022). "Therefore, CXCL9, CXCL10, and the CXCL11/CXCR3 axis have been regarded as potential cancer immune therapy targets." (PMID 35935945, 2022). "In addition, cancer cell-derived lymphotoxin can induce CXCL11 expression in stromal fibroblasts through the lymphotoxin receptor (LTBR)-NF-κB signaling pathway, thus contributing to EOC lymph node metastasis." (PMID 35269786, 2022). "CXCL11 was positively or negatively associated with TMB and MSI in different cancers." (PMID 35935945, 2022).
cancer (continued). "CXCL11 overexpression was associated with poor prognosis in multiple types of cancers, such as LGG, while it was associated with good prognosis in multiple types of cancers, such as COAD, SKCM, KIRP, and OV." (PMID 35935945, 2022). "CXCL11 is a controversial target for cancer treatment because it helps induce Tregs migration." (PMID 35702353, 2022). "Improved CXCL11 expression was related to an inconsistent prognosis in different cancers." (PMID 35935945, 2022). "Moreover, elevated CXCL11 expression was related to increased immunosuppressive factors except for VTCN1 in almost all types of cancer except THYM." (PMID 35935945, 2022). "As antigen processing and presentation pathway plays a crucial role in immune recognition of predicted (neo‐) antigen produced by cancer cells, we further investigated the relationship between neoantigen load and the CXCL11 expression signature by Pearson correlation coefficient." (PMID 34047476, 2021). "CXCL11 (CXC chemokine ligand 11) is a chemokine involved in the progression of various cancers." (PMID 33543590, 2021). "Together, these data indicate that cancer cells with DSBs could upregulate the expression of CXCL11 in vivo and in vitro." (PMID 34047476, 2021). "CXCL10 and CXCL11 increase the number of CXCR3-expressing cancer stem cells in BRCA cell lines." (PMID 34067089, 2021). "In this study, we found that the inhibition of GLS by compound 968 could increase the expression of CXCL10 and CXCL11 by cancer cells." (PMID 34944392, 2021). "The levels of CXCL10 and CXCL11 were limited under homeostatic conditions but could be secreted by cancer cells, endotheliocytes, leukocytes, and fibroblasts in response to different stimulants." (PMID 34944392, 2021). "Interferon-γ (IFN-γ) is the major inducer of three CXCR3 ligands, monokine induced by IFN-γ (MIG)/CXCL9, 10 kDa IFN-γ-induced protein (IP-10)/CXCL10 and IFN-inducible T cell α chemoattractant (I-TAC)/CXCL11 in mainly endothelial cells, monocytes, fibroblasts, and cancer cells." (PMID 34503058, 2021). "Finally, an interesting paper demonstrated how senescence of HUVEC cells induced by ionizing radiation and doxorubicin treatment increased MDA-MB-231 cancer cell proliferation and invasion through (CXCL11) secretion." (PMID 33322132, 2020). "Interestingly, CXCL11 was the only transcript in our analysis that allowed significant distinction between cancer of all stages and normal mucosa." (PMID 29163806, 2017). "Notably, chemokines like CXCL9, CXCL10, and CXCL11 are primarily produced by a variety of cell types, including monocytes, endothelial cells, fibroblasts, and cancer cells, in response to IFN-γ, and this response is further amplified by TNF-α, highlighting their role as pro-inflammatory cytokines." (PMID 40227454, 2025). "To uncover the association between the expression of CXCL11 and prognosis, we performed survival association analysis, including overall survival (OS), disease-specific survival (DSS), disease-free interval (DFI), and progression-free interval (PFI), across 33 types of cancers in TCGA." (PMID 35935945, 2022). "Therefore, the role of CXCL11 across cancers is still unclear." (PMID 35935945, 2022). "Thus, CAF-secreted CXCL11 may mediate the interaction between CAFs and their cohabitating cancer cells during HCC progression." (PMID 36435866, 2022). "It has been reported that the cancer autocrine molecule C-X-C motif chemokine 11 (CXCL11), accumulated in the TME, could increase the expression of stemness-related genes and maintain the stem cell features of α2δ1+ liver CSCs through chemokine (C-X-C motif) receptor 3 (CXCR3)/ERK1/2 signaling." (PMID 36293184, 2022). "Further investigation into CXCL11 might provide promising insights to improve cancer therapy." (PMID 35935945, 2022). "Our results revealed that CXCL11 could act as an independent prognostic factor in many cancers." (PMID 35935945, 2022). "CXCL11 might function as a prognostic and immunotherapy marker across cancers." (PMID 35935945, 2022).
cancer (continued). "CXCL11-dependent therapy may be a potential approach for cancer treatment." (PMID 33777950, 2021). "Moreover, CXCL11 was further down-regulated in liver metastases as compared to matched primary tumors, and above-threshold expression of CXCL9 and CXCL11 was significantly associated with longer cancer-specific and recurrence-free survival." (PMID 29163806, 2017). "CXCL9, CXCL10, and CXCL11 are selective ligands for the C‐X‐C motif chemokine receptor 3 (CXCR3) and are secreted by cancer cells." (PMID 40105652, 2025). "This includes the downregulation of key cytokines such as interleukin-17 (IL-17), chemokine ligand 3 (CCL3), C-X-C motif chemokine 11 (CXCL11), and chemokine ligand 5 (CCL5), providing a theoretical basis for targeting IGSF11 in cancer immunotherapy." (PMID 40867265, 2025). "Baseline expression levels of CXCL9, CXCL10, and CXCL11 were relatively low and comparable between MTAP-WT and MTAP-KO CL1–0 and 786–0 cancer cells, as well as between CL1–5 Mock and MTAP-expressing cells." (PMID 41246302, 2025). "In PTC, IFN-γ stimulates the release of chemokines, notably CXCL9 and CXCL11, which exert antiproliferative effects on PTC cells and restrict cancer cell migration." (PMID 40150133, 2025). "WDR43 different expression levels in various cancers were positively correlated with chemokines, including C-X-C motif chemokine ligand (CXCL) 9, CXCL10, and CXCL11." (PMID 39093744, 2024). "Seven chemokines (CCL18, CCL8, CXCL9, CXCL10, CXCL11, CCL26, and CCL7) showed positive relations in more than 25 cancer types." (PMID 38655053, 2024). "Contrary to our expectations, recent studies have shown that CXCL11 induces M2 polarization in the TME, promoting cancer growth." (PMID 39548525, 2024). "IFN-γ promotes migration of immune cells to TME by transcriptionally regulating the expression and secretion of CXCL9, CXCL10 and CXCL11 and their cognate receptor CXCR3 in T cells, NK cells, monocytes, DCs and cancer cells." (PMID 37646041, 2023). "Specifically, chemokines such as CXCL9, CXCL10, and CXCL11 and chemokine receptors such as CXCR5, CCR4, CCR8, and CCR1 were positively correlated with IGF2BP3 expression in various cancer types." (PMID 36761737, 2023). "V-Navo@gel treatment induced the expression of chemokines in cancer cells, including CCL2, CXCL10 and CXCL11 that drive the generation and recruitment of T cells, B cells and myeloid-derived cells." (PMID 37296221, 2023). "In terms of gene expression, SPP1, IKBKE, CXCL11, CXCL10, and other genes showed extensive high expression in COAD, ESCA, KIRC, READ, UCEC, and other cancers." (PMID 37666853, 2023). "CXCL11 and CXCL10 are secreted mainly by monocytes, endothelial cells, fibroblasts, and cancer cells in response to IFN-γ and are synergistically enhanced by IFN-α." (PMID 35432485, 2022). "ANK2-MT LUAD was characterized by high expression of chemokines (CXCL9, CXCL10, CXCL11, and CXCR3) involved in the recruitment of anti-cancer immune cells." (PMID 36539782, 2022). "We observed that immunostimulatory chemokines such as CXCL9, CXCL10, CXCL11, CCL4, and CCL5 were consistently down‐regulated for the tumors with high Hh activity across the 14 cancer types." (PMID 34841742, 2022). "To explore the relevance between CXCL11 expression and immune infiltration across cancers, we used the TIMER 2.0 database to investigate the correlation between CXCL11 expression and infiltrating immune cells." (PMID 35935945, 2022). "For other chemokines, CXCL11 was positively related to approximately all other chemokines except CCL14, CCL15, CCL16, CCL27, CCL28, CXCL6, and CXCL17 in almost all types of cancers." (PMID 35935945, 2022). "Our results revealed that CXCL11 expression was positively related to stromal scores, immune scores, and ESTIMATE scores across cancers." (PMID 35935945, 2022).